HMGA2 (high mobility group AT-hook 2)
Diseases named in the same sentence as HMGA2 in open-access papers (continued):
Sharing a sentence is not in itself a finding about the gene and the disease.
lung carcinoma (89 papers, 2008 to 2025). "In various cancers such as nasopharyngeal carcinoma and lung cancer, HMGA2 is often overexpressed or undergoes gene mutations, which are correlated with cell transformation, tumor proliferation, invasion, and metastasis." (PMID 38720887, 2024). "Meanwhile, plenty of studies showed that elevated HMGA2 expression in cancer tissues was associated with poor survival in patients such as lung cancer, oral squamous cell carcinoma, ovarian cancer and metastatic breast cancer." (PMID 29997523, 2018). "HMGA2 expression is usually elevated in tumors of colorectal and lung cancer patients in association with decreased survival." (PMID 27821801, 2016). "In particular, the expression of HMGA2 in lung carcinomas is frequently associated with the presence of metastases." (PMID 25859543, 2015). "For example, in lung cancer cells, a mature let-7e miRNA that encodes a m7G modification is capable of downregulating the stability and translation efficiency of the mRNA transcript encoding high mobility group protein 2 (HMGA2)." (PMID 37349851, 2023). "Indeed, HMGA2 protein expression is in some studies shown related to lung cancer development and progression, and inversely associated with lung cancer survival." (PMID 26858029, 2016). "Expression of HMGA2 has been implicated in bladder and lung cancers." (PMID 23704328, 2013). "Furthermore, seven of these genes (not including RPS4Y1) were implicated and studied in various cancers, but only HMGA2 was recently reported to be over expressed in lung cancer and inversely associated with survival." (PMID 19025616, 2008). "Moreover, HMGA2 expression is associated with a more malignant phenotype and a poor prognosis in squamous carcinomas of the oral cavity, nasopharyngeal carcinomas, glioblastoma, esophageal squamous carcinoma, lung cancer, and atypical teratoid/rhabdoid tumor." (PMID 32489328, 2020). "Many of the current targets being pursued based on the literature and studies of advanced lung cancer are focused on the pathways we found are active in the tumor organoid Hmga2-high state, such as the Wnt and Nfkb pathways." (PMID 39930268, 2025). "In an experimental in vitro setting, binding of microRNA let-7 to the 3’-untranslated region promoted degradation of HMGA2 RNA, and the growth of lung cancer cells was inhibited by transfection of let-7." (PMID 40033554, 2025). "This, in turn, leads to a reduction in levels of translated HMGA2 protein and subsequent arrest of lung cancer cell proliferation and migration." (PMID 37349851, 2023). "Vivo experiments have confirmed that overexpression of HMGA2 can inhibit the proliferation and metastasis of lung cancer, so HMGA2 is expected to become a new target for the treatment of lung cancer." (PMID 37033934, 2023). "In lung cancer, several reports have recognized miR-498-5p as a tumour suppressor by targeting HMGA2, tripartite motif containing 44 (TRIM44) or forkhead box O3 (FOXO3)." (PMID 37667197, 2023). "Many of the targets being pursued based on the literature and studies of advanced lung cancer are focused on the pathways we found are active in the tumor organoid Hmga2-high state, such as the Wnt and Nfkb pathways." (PMID 36993454, 2023). "The high expression of HMGA2 in lung cancer indicates a worse prognosis, which is consistent with our findings." (PMID 37033934, 2023). "Since let-7b-5p has been reported to inhibit HMGA2 expression in head and neck squamous cell carcinoma cells, HCC cells and lung cancer cells, we chose HMGA2 as a positive control." (PMID 37019900, 2023). "For example, Let-7a, an identified tumor suppressor, has been shown to inhibit the proliferation of lung cancer cells by regulating HMGA2 and myc." (PMID 35742854, 2022). "The m7G-let-7 miRNA can inhibit lung cancer cell metastasis by reducing the expression of target oncogenes, including high mobility group AT-hook 2 (HMGA2), RAS, and MYC, at the posttranscriptional level." (PMID 36553648, 2022).
lung carcinoma (continued). "In the literature, HMGA2 protein is one of the let-7c and 7d expression targets in studies conducted on ovarian, colon, breast, and lung cancer cell lines." (PMID 35943151, 2022). "In summary, the let-7f, as a major tumor suppressor regulatory factor, can exert its role in lung cancer via direct targeting genes such as HMGA2, SMARCAD-1, ARID-3, and FZD3 and can affect important processes, e.g. viability and proliferation of cancer cells." (PMID 35488374, 2022). "In previous studies, we demonstrated that HMGA2 increased the invasion and migration of breast and lung cancer cells." (PMID 34680349, 2021). "Mechanistically, let-7g acts on Ras and HMGA2 in lung cancers, which is consistent with findings of reduced Ras proteins and HMGA2 in let-7g expressing tumors." (PMID 33803619, 2021). "Expression of FHIT and miR-30c has been shown to be inversely correlated with HMGA2 expression in lung cancer and squamous cell carcinoma of the vulva." (PMID 31217897, 2019). "This is a well known tumor suppressor gene whose expression has been shown to exhibit an inverse correlation with HMGA2 in lung cancer, where FHIT enhances the expression of miR-30c and causes HMGA2 repression." (PMID 28423547, 2017). "For the first time in SCC of the vulva, we showed an inverse correlation betrween miR-30c and HMGA2 expression similar to the one previously reported in lung cancer." (PMID 27835588, 2016). "HMGA2 is highly expressed in most malignant epithelial tumors, including breast cancer, colorectal cancer, gastric cancer, lung cancer, melanoma, myeloid, oral cancer, ovarian cancer, pancreas cancer, pituitary adenomas." (PMID 26818837, 2016). "Several researches have revealed a new function and mechanism of HMGA2 as a competing endogenous to promote lung cancer progression." (PMID 26818837, 2016). "By consulting a previous study with lung cancer and other cancer lines, we adjusted the relative ectopic HMGA2 mRNA below the limit of pathological level (from 100 to 2000 multiples) in different WI38 cells infected with different doses of virus." (PMID 25300915, 2015). "While EGFR emerged as the most interesting candidate, other genes with intriguing connections to lung cancer biology, including HMGA2, BCL2, and others, will be the focus of future studies." (PMID 26556242, 2015). "An important role in the regulation of HMGA2 expression in lung carcinomas seems to be played by TTF-1." (PMID 25859543, 2015). "Taken together, these data suggested that MTDH and HMGA2 are direct target genes for miR-30c in lung cancer." (PMID 25340791, 2014). "HMGA2, or high mobility group AT-hook 2, is oncogenic in many cells, including lung carcinoma cells, and is regulated by the tumor-suppressive miRNA let-7." (PMID 23060898, 2012). "Ectopic expression of let-7b reduced HMGA2 expression and cell proliferation in a lung cancer cell line." (PMID 21029445, 2010). "The interaction between miRNAs and HMGA2 to promote EMT in lung cancer has been demonstrated." (PMID 38361784, 2024). "The functions of HMGA2 in lung cancer have been studied extensively." (PMID 38361784, 2024). "In past studies, abnormally high expression of HMGA2 has been observed in a variety of human cancers, such as esophageal squamous cell carcinoma,breast cancer, lung cancer, Thyroid cancer, melanoma, Colon cancer, Ovarian cancer, bladder cancer and other malignant tumors." (PMID 38304037, 2023). "In addition, another study elaborated the lung cancer therapy with HMGA2 (high-mobility group A2) suppressing small interfering RNA (siRNA) along with DOX by using chitosan-based NPs." (PMID 38202616, 2023). "The let-7f, as a major tumor suppressor regulatory factor via direct targeting genes (e.g. HMGA2), inhibits lung cancer cell viability and proliferation and could serve as a marker for the early diagnostic of NSCLC." (PMID 35488374, 2022). "Let-7 downregulation and HMGA2 overexpression occur during lung cancer development." (PMID 33668453, 2021).
lung carcinoma (continued). "In lung cancers, up-regulation of HMGA2 and down-regulation of let-7 has been reported." (PMID 34199293, 2021). "The downregulation of mature let-7e would cause overexpression of its target genes, such as the high mobility group AT-hook 2 (HMGA2), RAS and MYC driver genes of metastasis, thus making METTL1-mediated m7G editing important for inhibiting lung cancer cell migration." (PMID 34638933, 2021). "A previous paper reported that overexpression of HMGA2 in NSCLC could serve as a molecular marker in the progression of lung cancer." (PMID 32883329, 2020). "Crucially, Hmga2 was found to be a target of miR-33a in mouse and human lung cancer cells." (PMID 26980276, 2016). "MicroRNA let-7 suppressed proliferation in a lung cancer cell line via HMGA2 suppression." (PMID 27027350, 2016). "HMGA2 expression is elevated in many malignant neoplasms, and its overexpression is a poor prognostic factor for colon cancer, lung cancer, oral squamous cell carcinoma, ovarian cancer, and metastatic breast cancer." (PMID 27095441, 2016). "This ceRNA activity of the HMGA2 transcript was proposed to promote lung cancer progression." (PMID 25888444, 2015). "The high-mobility group protein A2 (HMGA2), known to regulate key developmental pathways in human embryonic stem cells and participate in transformation in lung cancer, was enriched in the human airway basal cells (27.9-fold enrichment), but not in the murine counterpart." (PMID 21572528, 2011). "For example, HMGA2 could regulate the cell metastasis of lung cancer." (PMID 36180890, 2022). "Numerous human malignancies such as ovarian cancer, lung cancer, hepatocellular carcinoma, and melanoma have been shown to have repression of multiple members of the let-7 family of miRNAs, thus promoting oncogenesis by depressing targets such as c-Myc, Ras, and HMGA2." (PMID 28693523, 2017). "An example is the let-7 family in lung cancer, which inhibits various oncogenes such as Rat Sarcoma (RAS), Myelocytomatosis Viral Oncogene Homolog (MYC), and High Mobility Group AT-hook 2 (HMGA2), thereby reducing the expression of cell cycle proteins." (PMID 39963112, 2025). "Conversely, let‐7 is a well‐known tumor‐suppressive miRNA in lung cancer, which targets oncogenes like RAS and HMGA2, resulting in the inhibition of tumor growth and spread." (PMID 39991629, 2025). "For instance, HMGA2 promoted proliferation, apoptosis, and EMT in lung cancer cells and was a biomarker for lung adenocarcinoma." (PMID 38361784, 2024). "In ADC/SCC, HMGA2, a gene crucial in proliferation, metastasis, and epithelial-mesenchymal transition (EMT) in lung cancer, exhibited upregulation." (PMID 38383412, 2024). "The findings showed that the codelivery of HMGA2, siRNA, and DOX through innovative CMDTMChiNPs was a novel therapeutic method with prodigious potential effectiveness for lung cancer treatment." (PMID 38202616, 2023). "Particularly, this family suppresses the proliferation of tumors, like breast and lung cancer, by regulating the expression of critical oncogenes including RAS, MYC, and HMGA2." (PMID 36062186, 2022). "For example, HMGA2 is a binding partner of PCAT6 and contributes to PCAT6-mediated CRC, as well as EZH2 in CRC and lung cancer." (PMID 34327141, 2021). "For example, in lung cancer cells, the upregulation of miR-495 repressed HMGA2 expression by binding to its 3′-UTR and inhibited cell proliferation; HMGA2 upregulation reversed this inhibition." (PMID 31963852, 2020). "This family in particular inhibits the progression and invasiveness of numerous tumors, including lung cancer, by regulating the expression of key oncogenes such as RAS, MYC, and HMGA2." (PMID 31031083, 2019). "On the TS miRNA side, let-7 has been found as a tumor suppressor in human lung cancer and its target genes including oncogenes RAS and HMGA2." (PMID 29312571, 2017).
lung carcinoma (continued). "The lung cancer cell line study of knockdown and overexpression of TTF-1 revealed TTF-1 mediated High Mobility Group AT-Hook 2 (HMGA2) protein involved with epithelium-mesenchymal transformation." (PMID 29079814, 2017). "Overexpression of Hmga2 titrates away has-let-7s from Tgfbr3, freeing and increasing Tgfbr3 to triggerAgo2 and TGF-β signaling pathway activity, eventually leading to lung cancer progression." (PMID 26872371, 2016). "In accord with these results, lung cancer cells, A549, H460 and H1299, with enhanced expression of miR-30c, or MTDH or HMGA2 knockdown exhibited a decrease in cell invasion and migration in vitro." (PMID 25340791, 2014). "The let-7 miRNAs, for example, which are down-regulated in lung cancer, negatively regulate the oncogenes RAS and HMGA2, suggesting their possible role in the activation of oncogenes in lung cancer." (PMID 21541038, 2011). "It was shown that miR-195 could target and downregulate HMGA2 to induce EMT and proliferation in lung cancer cells." (PMID 38361784, 2024). "Furthermore, it has been reported that MMP1, HMGA2, TRPA1, and PLAU are highly expressed in various subtypes of lung cancer." (PMID 35354498, 2022). "The effect of let-7 on HMGA2 was determined by multiple target sites in the 3’ untranslated region (UTR), and overexpression of the HMGA2 ORF without a 3’UTR rescued the growth-suppressive effect of let-7 on lung cancer cells." (PMID 34199293, 2021). "It was reported that PP4R1 could cooperate with HMGA2 and promote EMT through activating MAPK/ERK signaling pathway in lung cancer cells." (PMID 33668453, 2021). "HMGA2 staining was negative in the adipose tissue observed on the twenty tumor-free bronchial surgical margins of resection specimens of lung carcinoma and on the 3 cases excluded initially because of normal endoscopic appearance." (PMID 28228139, 2017). "Previous studies have not investigated this fully in specific histological lung cancer subgroups, but have shown that the HMGA2 protein is involved in the transformation of lung cancer cells." (PMID 26858029, 2016). "MRNAs of Hmga2 and BRAF could induce lung cancer progression and lymphoma formation respectively, which suggests these mRNAs may be a therapeutic targets for these malignant diseases." (PMID 26872371, 2016). "A recent study indicated that Hmga2 mRNA can promote lung cancer progression through ceRNA function independent of its protein-coding function." (PMID 26872371, 2016). "A recent study also found that high-mobility group A (HMGA2), a non-canonical transcriptional factor, promoted lung cancer progression independent of its protein-coding function." (PMID 26123544, 2015). "Critically, the authors found that HMGA2 and TGFBR3 transcripts were expressed at similar levels, and that total let-7 family expression was within an order of magnitude of these transcripts in the lung cancer cell line tested." (PMID 25888444, 2015). "Next, we were interested in identifying the expression patterns of FHIT, miR-30c, MTDH and HMGA2 in lung cancer progression and examined their mRNA levels in normal, non-metastatic and metastatic lung tissues." (PMID 25340791, 2014). "HMGA2 is a non-histone chromatin factor that is primarily expressed in undifferentiated tissues, tumors of mesenchymal origin and lung cancer." (PMID 20302635, 2010). "However, additional transcription factors may be involved including HMGA2, ZEB1 and TWIST2, known to be involved in lung cancer." (PMID 41184222, 2025). "Additionally, the deregulation of Let-7 miRNA has been demonstrated to be a feature of numerous cancers specifically lung cancer, Let-7a miRNA may target a number of genes, including RAS, Myc, Hmga2, and Cyclin D1." (PMID 37845669, 2023). "Additionally, HMGA2 and KLF4 regulation are able to promote PI3K/Akt phosphorylation, resulting in increased drug resistance, and miR-26a interacts with HMGA2 and miR-145 with KLF4 to promote DDP-resistance in lung cancer cells." (PMID 35444536, 2022).
lung carcinoma (continued). "Indeed, HMGA2 functions as a ceRNA, competing with the transforming growth factor beta receptor 3(TGFBR3) for let-7, thus allowing for the heightened expression of TGFBR3 and subsequent lung cancer progression." (PMID 26123544, 2015). "In addition, we observed that MTDH mRNA, but not HMGA2 mRNA, was decreased in miR-30c-transfected lung cancer cells, A549, H460 and H1299 and showed inverse correlation with miR-30c in lung primary tumors." (PMID 25340791, 2014). "Finally, to determine if our experimental findings could be relevant to the pathogenesis of human lung cancer, we examined the expression pattern of FHIT, miR-30c, MTDH and HMGA2 in primary tumor tissues and matched lymph node metastatic tissues." (PMID 25340791, 2014). "Finally, we demonstrate that the expression pattern of FHIT and miR-30c is inversely correlated with that of MTDH and HMGA2 in normal tissue, non-metastatic and metastatic tumors, serving as a potential biomarker for metastasis in lung cancer." (PMID 25340791, 2014). "There was a negative correlation between let-7a expression and HMGA2 expression in LCSS patients and this was in consistent with the previously reported results in oral squamous cell carcinoma, neuroendocrine tumors, and lung cancer." (PMID 32432318, 2020).